SELE (selectin E)
Diseases named in the same sentence as SELE in open-access papers (continued):
Sharing a sentence is not in itself a finding about the gene and the disease.
tumor (continued). "Further, a direct effect of lovastatin on tumor cell adhesion was reported in HUVEC cells treated with a combination of lovastatin and all-trans retinoic acid through the reduction of E-selectin expression." (PMID 37760764, 2023). "Highly N-acetylated COS (NACOS) inhibits TNF-alpha-induced E-selectin expression in ECs via the JNK/NF-κB pathways, potentially attenuates tumor cell adhesion with ECs." (PMID 33262947, 2020). "Furthermore, in vitro studies suggest that omega-3 and omega-6 fats obtained from the diet may impact CRC tumor cell adhesion by modulating membrane fatty acid composition and E-selectin expression on LSECs, and ultimately increasing liver metastatic burden in vivo." (PMID 32230953, 2020). "E-selectin expressed on activated ECs interacts with a variety of ESL present on circulating leukocytes and tumor cells." (PMID 24386459, 2013). "Protein-protein interaction analysis identified four hub genes-ASPN, SELE, ACKR1 and ABCB1-integrating ECM remodelling, endothelial-immune modulation and xenobiotic transport, reinforcing an immune-attenuated, metabolically adapted tumour landscape." (PMID 42194092, 2026). "Furthermore, as compared to normal samples, tumor samples had higher levels of SELE and SACS expression, and tumor samples had a wide range of expression for these genes." (PMID 36064367, 2022). "These SLX-Lipo-ICG could accumulate in the regions of inflammation or tumor owing to the interaction of SLX and E-selectin, which enhanced E-selectin expression by inflammatory cytokines, such as TNF, in vascular endothelial cells." (PMID 31426531, 2019). "Shear flow experiments showed for the first time that sulfatides expressed on the surface of tumour cells mediate their rolling on P-selectin-expressing cells, and do not interact with E-selectin-expressing cells." (PMID 30400820, 2018). "Given the constitutive E-selectin expression in dermal microvessels, it would be expected that exofucosylated CAR T-cells would migrate to the skin, but immunoreactivity would only be triggered in presence of relevant infiltrating tumor cells." (PMID 30687313, 2018). "After DV is attracted to the tumor areas, infiltration then becomes critical, as a review study found that 93.8% of melanoma samples showed no P and E-Selectin expression on CD31+ vessels." (PMID 25592450, 2015). "In parallel, upon RUNX2 knockdown, we have observed a predominant and strong downregulation of gene nodes known to be implicated in EOC tumorigenesis (PTGS1/COX1, FGF2, IL1A, Sapk, C/ebp, SELE, UBQLN1, PSAT1, ALDH1A1, GDF15, MTHFD2), including EOC tumor invasion/metastasis (MMP1, MMP13, Creb);." (PMID 24124450, 2013). "In contrast, SELE expression was specific to endothelial cells in both tumor and nontumor tissues." (PMID 39744943, 2025).
cancer (193 papers, 1993 to 2025). A tumor composed of atypical neoplastic, often pleomorphic cells that invade other tissues. "The occurrence and development of cancer are closely related to the accumulation of genetic variations, suggesting a potential oncogenic role for SELE mutations." (PMID 39440769, 2025). "E-selectin, encoded by SELE, is a crucial cell-adhesion molecule specifically expressed on the surface of endothelial cells, particularly attracting cancer cells by interacting with glycoproteins." (PMID 39744943, 2025). "In acute myeloid leukemia engrafted mice, E-selectin expressed by cancer cells was associated with a chemoresistance promoted through the Wnt pathway." (PMID 40071851, 2025). "This study's findings confirm the importance of SELE polymorphisms in cancer risk prediction." (PMID 36617649, 2022). "Upon Mint3-dependent VEGF secretion by IMs, E-selectin expression in endothelial cells and vascular permeabilization of cancer cells are elevated." (PMID 36831085, 2023). "E-selectin enhances the adhesion of cancer cells to the sinusoidal endothelial cells, promoting metastasis to the liver." (PMID 36497322, 2022). "Cimetidine is able to block E-selectin expression on vascular endothelium, and this inhibits adhesion of cancer cells to endothelial cells, suggesting that cimetidine can prevent metastasis development by suppression of E-selectin/SLeX and SLeA interaction." (PMID 35158915, 2022). "Endothelial cells express SELE, a key adhesion molecule known for its involvement in facilitating cell-cell contacts between cancer cells and endothelial monolayers during metastasis." (PMID 36617649, 2022). "Due to E-selectin expression on bone marrow microvascular endothelium, it is frequently the site of cancer metastasis." (PMID 34206154, 2021). "The authors found that ANP inhibited the adhesion of cancer cells to pulmonary arterial and micro-vascular endothelial cells by suppressing the E-selectin expression that is promoted by inflammation." (PMID 29324747, 2018). "In turn, this triggers E-selectin expression by endothelial cells and enhances the binding and extravasation of the cancer cells." (PMID 28903453, 2017). "This is a variant of the tyrosine kinase FGF glycoreceptor, raising the possibility that its binding to E-selectin elicits signaling in the adhering cancer cells." (PMID 28903453, 2017). "Very recently, myeloid-derived suppressor cells have been shown to promote the arrest of cancer cells via IL-1β-mediated E-selectin expression on endothelial cells." (PMID 28680883, 2017). "We have previously reported that E-selectin expression on the endothelial cell surface mediates shear-resistant adhesion and migration of circulating cancer cells via interaction with CD44." (PMID 27220365, 2016). "CD44 is a glycoprotein that mediates the interaction of cancer cells to E-selectin expressed on endothelial cells." (PMID 25343626, 2014). "E-selectin expressed by endothelial cells is a well-recognized mediator of adhesion of cancer cells and cells of hematopoietic origin." (PMID 22970241, 2012). "E-selectin expression on the vasculature is transcriptionally induced in the presence of inflammatory stimuli, and subsequently, E-selectin expression is commonly observed in pathological inflammation, including cancer." (PMID 20927342, 2010). "Andrographolide inhibits the adhesion of cancer cells to the activated endothelium by blocking E-selectin expression." (PMID 20465823, 2010). "We also demonstrated that ESTA-1 bound efficiently to E-selectin expressing endothelium of human and mouse carcinomas." (PMID 20927342, 2010). "Moreover, certain drugs have demonstrated direct effects on E-selectin expression, thereby influencing cancer progression." (PMID 39100681, 2024). "Suppression of surgically induced systemic inflammation by MP administration might prevent hematogenous cancer metastases by suppressing the induction of E-selectin expression in the vascular endothelium." (PMID 33737522, 2021).
cancer (continued). "Furthermore, a recent study has shown that ANP inhibits the adhesion of cancer cells to atrial and vascular endothelial cells by suppressing the E-selectin expression that is promoted by inflammation." (PMID 28570595, 2017). "In other types of cancers, these interactions may be mediated by E-selectin expressed on endothelial cells in the HEV and E-selectin ligands expressed on cancer cells." (PMID 25380524, 2014). "We further checked whether the SLA expression on HBx-transfected cells and E-selectin expressed on TNF-α-stimulated endothelial cells is closely associated with cancer cell to endothelial cell interactions for metastatic potential, using antibodies against SLX/A and E-selectin." (PMID 25255877, 2014). "Such sialylated glycoprotein ligands for E-selectin expressed on tumor cells include CD44, P-selectin glycoprotein ligand (PSGL-1), and CD24 as cancer stem cell markers." (PMID 36754910, 2023). "The expression of SELE and SACS increased considerably in cancer samples compared to normal samples, according to the results of RT-qPCR data (P < 0.01)." (PMID 36064367, 2022). "Our data are the first to report the miRNA modulation of E-selectin expression and functions in an in vitro model of TEM of cancer cells." (PMID 29402939, 2018). "Our analyses of the gene expression data in (bulk) cancer tissues show that there is no or little correlation between CMAS and any siglec gene (SIGLEC1-16), selectin gene (SELE, SELL, and SELP) or their total expressions (data not shown)." (PMID 32296639, 2020).
infection (58 papers, 2011 to 2025). The state of being infected such as from the introduction of a foreign agent such as serum, vaccine, antigenic substance or organism. "As shown, E-selectin expression (labeled with Cy3) around the BMECs (labeled with anti-CD31-FITC) was significantly upregulated by infection, while rTGFβ1 treatment prevented the E-selectin induction." (PMID 38360663, 2024). "Secondly, E-selectin expression is known to be rapidly down regulated during infection to protect the host against harmful effects of inflammation." (PMID 24324686, 2013). "This enables ligand-specific transduction of E-selectin-expressing endothelial cells, following infection with the MHES-retargeted virus." (PMID 20965218, 2011). "In related studies, we observed that live and paraformaldehyde (PFA)‐killed N. meningitidis exhibit varying capacities in modulating host immunity, and consequently, we aimed to establish how infection with killed N. meningitidis may impact on endothelial E‐selectin expression." (PMID 26153406, 2016). "In contrast, untreated infection networks were dominated by inflammatory mediators (IL6, CXCL10, CCL2, VCAM1, SELE) and antiviral sensors (DDX58, OAS1, IFI44, IFI6), which reflect strong cytokine and interferon-driven immunity." (PMID 41480150, 2025). "The expression of E-selectin (SELE), P-selectin (SELP), and integrin β2 (ITGβ2) also increased gradually in the Yb2- and cYb2ΔsspA-infected ducks as the infection time increased." (PMID 38594770, 2024). "In this study, we identified several proteins (FABP4, LEP, RARRES2, MSTN, C2, SELE and IL6) that belong to a family of chronic pro-inflammatory cytokines and are primarily produced in response to infection or stress, some of which are mainly produced by adipose tissue (FABP4, LEP and RARRES2)." (PMID 38548792, 2024). "Interestingly, infection with the non-piliated pilD mutant strain induced E-selectin expression to a much lesser extent when compared to the wild-type strain, highlighting the role of bacterial pilus-mediated adhesion." (PMID 41406015, 2025). "Moreover, upregulated E-selectin expression was found to be localized to the gastric mucosa rather than being a systemic response to the infection." (PMID 26087062, 2015). "However, when the cord was treated with rhTNF-α for 4 h prior to infection, a marked increase in transgene expression from MHES-StrepGpcAdluc was observed, likely reflecting up-regulation of E-selectin expression on the surface of polarised endothelial cells allowing their transduction." (PMID 20965218, 2011). "It is likewise in accordance with the observed significant increase in SELE (E-selectin) expression during 8067 and T15 but not S10 infection, suggesting that the recruitment of immune cells to control the infection is initiated rapidly during 8067 and T15 infection." (PMID 38276150, 2023). "Additionally, a significant increase in E-selectin (SELE) gene expression was observed only during 8067 and T15 infection, not during S10 infection." (PMID 38276150, 2023). "Similarly, in the present study, we found a marked increase in ICAM-1 expression in the brain on day 6 of infection, VCAM-1 and P-selectin had more modest increases and E-selectin expression was not significantly different in uninfected and saline-treated mice." (PMID 21649904, 2011).
cardiovascular disease (37 papers, 2009 to 2025). "Previously, genetic variants of SELE were strongly associated with cardiovascular disease." (PMID 36078037, 2022). "Among these genes, TYW1B, FCER2, SELE, and SDC-1 had some degree of connection with cardiovascular diseases including AF." (PMID 36078037, 2022).
inflammation (15 papers, 2014 to 2025). Aberrant reaction of the microcirculation characterized by movement of fluid and leukocytes from the blood into extravascular tissues. "Our data indicates that emodin potently inhibits LPS-induced pulmonary inflammation, pulmonary edema and MCP-1 and E-selectin expression, and that these effects were very likely mediated by inactivation of NF-κB in mice." (PMID 25347274, 2014).
psychiatric disorder (1 paper, 2020). A disorder characterized by behavioral and/or psychological abnormalities, often accompanied by physical symptoms. "Although the enrichment does not reach significance following multiple hypothesis testing comparison, it is worth noting that additional genes are implicated in psychiatric disorders (GABRE, GNRH1, FMO1, FLG, SELE, NQO2)." (PMID 33169669, 2020).
SELE also shares sentences with these, for which no sentence is quoted: type 2 diabetes (37 papers); Insulin resistance (24); Hyperglycemia (18); metabolic syndrome (18); myocardial infarction (15); thrombosis (15); asthma (10); lung carcinoma (9); myeloma (9); endotoxemia (8); essential hypertension (8); glaucoma (8); periodontitis (8); preeclampsia (8); ovarian carcinoma (7); pulmonary hypertension (7); atopic dermatitis (6); cerebrovascular disease (6); renal disease (6); venous thromboembolism (6); allergic rhinitis (5); dengue (5); Graves disease (5); Hypercholesterolemia (5); inflammatory bowel disease (5); pneumonia (5); prediabetes (5); systemic inflammatory response syndrome (5); acute coronary syndrome (4); acute GVHD (4).
A further 257 diseases each share a sentence with SELE in 4 papers or fewer.